NOTCH3 (notch receptor 3)
Diseases named in the same sentence as NOTCH3 in open-access papers (continued):
Sharing a sentence is not in itself a finding about the gene and the disease.
papillary thyroid cancer (4 papers, 2019 to 2022). "For example, Hsa_circ_0058124 facilitated papillary thyroid cancer progression and invasiveness via the NOTCH3/GATAD2A axis." (PMID 36072578, 2022).
renal carcinoma (4 papers, 2015 to 2022). A carcinoma arising from the epithelium of the renal parenchyma or the renal pelvis. "Through cell cycle and HIF-2α regulation, Notch3 promotes the proliferation of renal cancer cells." (PMID 33968978, 2021).
thyroid cancer (4 papers, 2019 to 2024). "Moreover, the dedifferentiation process, typical of thyroid oncogenesis, seems to be correlated with the loss of NOTCH3 expression, whereas the doxycycline-induced NOTCH3 activation restores the differentiated phenotype and has an antiproliferative effect in thyroid cancer cell lines (TT, FTC)." (PMID 31443481, 2019). "Overexpression of the Notch signaling pathway, including that of Notch1, Notch3, and Hes1, is directly associated with a differentiation phenotype (NIS, TPO) expression of both thyroid cancers and TSH-stimulated normal thyroid cells." (PMID 33995657, 2021). "In contrast, suppression of Notch3 by siRNA could silence the expression of thyroid-specific genes in thyroid cancers." (PMID 33995657, 2021). "Circ_0058124 enhances the progression of thyroid cancer via the NOTCH3/GATAD2A signaling." (PMID 34290668, 2021).
aneurysm (3 papers, 2019 to 2022). Bulging or ballooning in an area of an artery secondary to arterial wall weakening. "Nevertheless, rupture of IA is the most severe prognostic indicator for IA patient, and the risk of aneurysm rupture is associated with the degree of inflammation in the arterial wall, which in turn could be aggravated by upregulated NOTCH3 in neutrophils." (PMID 31339861, 2019). "Blocking Notch3 activation with DAPT in the early aortic development of Fbn1mgR/mgR mice attenuated aneurysm enlargement and preserved elastic fiber integrity, therefore prolonging the lifespan of Fbn1mgR/mgR mice." (PMID 35211631, 2022). "Surprisingly, Notch3 overexpression appears to confer adaptive responses against aneurysm growth, including inhibition of SMC contractile gene overexpression, promotion of SMC proliferation, reduction of apoptosis and decreased MMP activity." (PMID 31886938, 2020). "While these changes suggest a largely protective role for Notch3 with regards to aneurysm biology, Notch3 may act as an inhibitor of ELN expression in vitro." (PMID 31886938, 2020). "Intriguingly, we report that ERK drives Notch3 overexpression, a potential protective pathway for tissue remodelling in response to MFS aneurysm formation." (PMID 31886938, 2020). "Given the novel finding that Notch3 is up‐regulated specifically in MFS aortic aneurysm specimens, our initial theory was that this pathway might contribute to focal aneurysm development." (PMID 31886938, 2020).
aortic aneurysm (3 papers, 2019 to 2022). A ruptured aneurysm located in the wall of the proximal portion of the descending aorta proceeding from the arch of the aorta. "During aortic development of MFS (Fbn1mgR/mgR) mice, increased Notch3 activation contributes to aortic aneurysm formation." (PMID 35211631, 2022). "Our results suggest that inhibiting Notch3 activation may provide a strategy to prevent and treat aortic aneurysms in MFS." (PMID 35211631, 2022). "We investigated the impact of Notch3 in aortic aneurysm development in MFS." (PMID 35211631, 2022). "Enhanced Notch3 activation in MFS contributed to aortic aneurysm formation in MFS." (PMID 35211631, 2022). "Since we found that NOTCH1 and NOTCH3 levels are differentially expressed in the aortic aneurysm samples, we next evaluated if they might regulate PDE5 expression in VSMCs in vitro." (PMID 31434939, 2019). "Our results suggest that inhibition of the effect of Notch3 signaling in the early aortic development of MFS may be a useful strategy to prevent and treat aortic aneurysms in MFS." (PMID 35211631, 2022).
arteriovenous malformations (3 papers, 2015 to 2022). "Furthermore, Notch1+/−; Notch3−/− mice displayed retinal AVMs, pointing to a key role for pericytes in normal vascular function and indicating that pericyte dysfunction due to Notch deficiency contributes to arteriovenous malformations." (PMID 26563570, 2015). "NOTCH3 is required for SMC maturation and deficiency causes pericyte dysfunction and arteriovenous malformations." (PMID 35926050, 2022). "Our findings suggested that Notch 4, and more importantly, Notch 3, may play a role in the development and pathobiology of human arteriovenous malformations." (PMID 25846406, 2015). "We have demonstrated that Notch 3 and 4, and not Notch 1, were highly increased in human arteriovenous malformations." (PMID 25846406, 2015).
B-Acute Lymphoblastic Leukemia (3 papers, 2020 to 2023). "The NOTCH3 gene is frequently epigenetically silenced in B-cell acute lymphocytic leukemia (B-ALL) cells, pointing to a broader tumor-suppressor role of NOTCH3 in B-cells." (PMID 32570839, 2020). "Recently, NOTCH3, PAX5, CBFB, and particularly ACD were shown to drive the activated RAS pathway and monosomy 7 to B-acute lymphoblastic leukemia." (PMID 36980962, 2023).
cerebral amyloid angiopathy (3 papers, 2017 to 2025). "Our findings align with previous studies suggesting that alterations in NOTCH3 cleavage may trigger the deposition of amyloid peptides in VSMCs, as observed in CADASIL and cerebral amyloid angiopathy." (PMID 39841284, 2025).
cervical carcinoma (3 papers, 2019 to 2022). A carcinoma arising from either the exocervical squamous epithelium or the endocervical glandular epithelium. "Cervical carcinomas patients positive for nuclear Notch3 expression showed shorter overall survival when compared with Notch3-negative patients; thus, Notch3 is a possible prognostic marker in cervical carcinomas." (PMID 36627893, 2022). "The findings suggest that Notch-1 and Notch-3 may play an important role with synergistic effect of HPV in regulating development and proliferation of cervical cancer through the deregulation of Notch signalling." (PMID 31417656, 2019).
choroid plexus tumors (3 papers, 2013 to 2019). "Different from Notch2, Notch3 has been implicated in choroid plexus tumors, and knockdown of Notch3 only slightly affect the viability of U87 cells,which is consistent with our observation." (PMID 30606241, 2019). "In addition, mutations in Twist-related protein-1 and constitutively active Notch 3 promote proliferation and invasion in choroid plexus tumors." (PMID 25426018, 2014). "Only 2 recent studies by Gaiano and Eberhart’s groups have implicated NOTCH3 in brain development and brain tumors by demonstrating that retroviral injection of the active NICD3 into forebrain ventricles of mouse embryos resulted in formation of postnatal choroid plexus tumors." (PMID 24143218, 2013).
chronic kidney disease (3 papers, 2015 to 2025). Impairment of the renal function secondary to chronic kidney damage persisting for three or more months. "In summary, we have reported a case of CADASIL-like cerebral lesions and symptoms with a novel heterozygous missense mutation of the NOTCH3 gene, which also showed chronic renal failure with granular deposits in the renal arterioles." (PMID 25834748, 2015). "Notch3 inhibition has a dual-therapeutic effect in HIV-related chronic kidney disease." (PMID 39910908, 2025). "We hypothesized that targeting NOTCH3 activation constitutes an effective therapy for HIV-related chronic kidney disease." (PMID 39910908, 2025). "Thus, Notch3 deletion/inhibition has a dual-therapeutic effect in HIV-related chronic kidney disease, which might extend to other HIV-related pathologies." (PMID 39910908, 2025). "Notch3 activation in pericytes of ABMR transplanted kidneys has been associated with negative transplant outcomes, highlighting the importance of addressing pericyte dysfunction as a potential treatment strategy to prevent the progression of acute kidney injury to chronic kidney disease post-ABMR." (PMID 39910824, 2025).
chronic obstructive pulmonary disease (3 papers, 2016 to 2022). A chronic and progressive lung disorder characterized by the loss of elasticity of the bronchial tree and the air sacs, destruction of the air sacs wall, thickening of the bronchial wall, and mucous accumulation in the bronchial tree. "Recently, it was shown that deletion of Notch3 leads to an expansion of basal cells, a hallmark of smokers and individuals with chronic obstructive pulmonary disease (COPD)." (PMID 27107715, 2016). "Additionally, in H9C2 cells, miR-1 targets Notch3, but the role of Notch3 in cardiac arrhythmia remains to be investigated." (PMID 34527667, 2021).
Encephalopathy (3 papers, 2015 to 2022). Encephalopathy is a term that means brain disease, damage, or malfunction. "In this study, we identified a null homozygous NOTCH3 mutation in a patient affected by recessive early-onset leukoencephalopathy, which progressed to severe encephalopathy with white matter cavitations and evidence of vascular lesions." (PMID 25870235, 2015).
endothelial dysfunction (3 papers, 2015 to 2023). In vascular diseases, endothelial dysfunction is a systemic pathological state of the endothelium (the inner lining of blood vessels) and can be broadly defined as an imbalance between vasodilating and vasoconstricting substances produced by (or acting on) the endothelium. "In contrast, the development of AVMs likely arises from a combination of endothelial dysfunction due to Notch1 heterozygosity, in addition to mural cell dysfunction caused by combined deficiency of Notch1 and Notch3." (PMID 26563570, 2015). "Our data are particularly interesting in the context of recent studies validating antibody inhibition of Notch3 as a potential PH treatment, which could reduce not only established Notch3 proliferative effects but also vascular hyperreactivity and endothelial dysfunction that we have highlighted." (PMID 37254738, 2023).
familial partial lipodystrophy (3 papers, 2024 to 2025). "Description of a novel subtype of Familial partial lipodystrophy (FPLD) caused by gain-of-function missense variants in the negative regulatory region of the NOTCH3 gene." (PMID 40835790, 2025).
head and neck squamous cell carcinoma (3 papers, 2021 to 2025). A squamous cell carcinoma that arises from any of the following anatomic sites: lip and oral cavity, nasal cavity, paranasal sinuses, pharynx, larynx, and salivary glands. "Analysis of matched pairs of head and neck squamous cell carcinoma (HNSCC) lines from primary and metastatic sites identifies differential expression of Notch3 components, and suppression of Notch3 improves survival in mouse models of metastatic HNSCC." (PMID 37202533, 2023).
Headache (3 papers, 2022 to 2025). Cephalgia, or pain sensed in various parts of the head, not confined to the area of distribution of any nerve. "Studies with NOTCH3 genetic variants as a diagnostic and therapeutic factor, especially in the context of headaches, should conduct further research on larger groups of people, including relatives and those without a family history of the condition." (PMID 37873835, 2023). "Clinical features including headache associated with NOTCH3 (chr19:15192257 T>G) are described for the first time." (PMID 37873835, 2023). "It seems that different NOTCH3 variants may contribute to the differential presentation of a CADASIL headache, highlighting the diagnostic and prognostic value of headache characteristics in this disease." (PMID 37873835, 2023). "This study investigated NOTCH3 genetic variants in CADASIL patients and their potential association with headache types." (PMID 37873835, 2023).
Hyperglycemia (3 papers, 2021 to 2025). An increased concentration of glucose in the blood. "Concurrently, siRNA-mediated gene silencing of Notch3 inhibited VSMC proliferation and expression of autophagy markers in high glucose-treated cells, suggesting a role of Notch3 in hyperglycemia-induced autophagy and VSMC proliferation." (PMID 40940776, 2025). "For instance, Notch3 is profoundly downregulated in diabetic mouse pericytes and in hyperglycemia-induced human retinal pericytes, and the suppression of Notch3 in pericytes results in barrier dysfunction of EC monolayers." (PMID 34769308, 2021). "In diabetic vascular complications, the γ-secretase target notch receptor 3 (NOTCH3) and its ligand delta-like canonical Notch ligand 4 (DLL4) are central mediators of vascular basement membrane thickening, influenced by hyperglycemia and inflammatory factors." (PMID 41359105, 2025).
hyperlipidemia (3 papers, 2021 to 2024). "In our case, 3 confirmed CADASIL patients from the same family carrying the same NOTCH3 mutation had different clinical phenotypes, but all had a history of hyperlipidemia." (PMID 39465783, 2024).
Insulin resistance (3 papers, 2019 to 2025). Increased resistance towards insulin, that is, diminished effectiveness of insulin in reducing blood glucose levels. "J 2 (JAG2), NOTCH3, CDKN1A, HES1, and MAPT are novel biomarkers for the development of insulin resistance." (PMID 30678306, 2019).
ischemia (3 papers, 2013 to 2024). A hypoperfusion of the BLOOD through an organ or tissue caused by a PATHOLOGIC CONSTRICTION or obstruction of its BLOOD VESSELS, or an absence of BLOOD CIRCULATION. "Additional studies in large patient-control series and other ethnicities are required to fully elucidate the role of NOTCH3 variation in disease and the underlying pathomechanism that results in ischemia." (PMID 24086431, 2013).
lung disease (3 papers, 2021 to 2025). "Herein, we provide a comprehensive summary of the role of NOTCH3 signalling in regulating repair/regeneration of the adult lung, its association with development of lung disease and potential therapeutic strategies to target its signalling activity." (PMID 36052538, 2022). "Success in these studies should lead to further improvement of existing therapeutic strategies to target NOTCH3 signalling and ultimately facilitate the development of new treatments for human lung disease." (PMID 36052538, 2022). "Finally, we debate the potential and means of targeting NOTCH3 signalling as a therapeutic strategy for treatment of lung disease." (PMID 36052538, 2022). "Furthermore, both in vitro and in vivo pre-clinical models of lung disease have been utilised to successfully demonstrate the potential of targeting NOTCH3 signalling activity as a viable therapeutic strategy for treatment of human lung disease." (PMID 36052538, 2022). "Therefore, strategies to specifically target NOTCH3 signalling provide an attractive therapeutic option to treat and control lung disease pathogenesis (Refs 59, 60, 61, 62, 63, 64, 65, 68, 136)." (PMID 36052538, 2022).
lung squamous cell carcinoma (3 papers, 2013 to 2024). "The expression of the Notch3 protein in lung squamous cell carcinoma, adenocarcinoma, small cell carcinoma and corresponding non-tumor tissues was detected by immunohistochemistry." (PMID 23420695, 2013). "It was demonstrated that Notch3 had a stronger positive degree of expression in lung squamous cell carcinoma and adenocarcinoma compared with the corresponding non-tumor tissue (P<0.01)." (PMID 23420695, 2013).
Nephropathy (3 papers, 2022 to 2025). A nonspecific term referring to disease or damage of the kidneys. "We found activation of Notch3 in renal cells of the HIV-1 transgenic mouse model (HIV-Tg26) and in patients with HIV-associated nephropathy." (PMID 39910908, 2025). "Recent studies have shown that Notch3 is abnormally activated, plays crucial roles in nephropathy, and directly affects the prognosis as well as the outcome of nephropathy." (PMID 35953831, 2022).
Onset (3 papers, 2018 to 2025). The age group in which disease manifestations appear. "Nevertheless, our study suggests a potential pathogenic link between NOTCH3, CSF1R, and sporadic late-onset AD, which warrants further investigation." (PMID 29544907, 2018).
Oral Squamous Cell Carcinoma (3 papers, 2016 to 2025). "A previous study in oral squamous cell carcinoma had shown that NOTCH3 is indeed overexpressed in CAFs, contributes to angiogenesis, and has been proposed as a therapeutic target." (PMID 39245631, 2025). "Analysis of human oral squamous cell carcinoma patient samples rendered presence of NOTCH3+αSMA+CAFs in the vicinity of cancer nests leading to poor overall survival rate." (PMID 38269089, 2023). "Apart from NOTCH1 and NOTCH2, NOTCH3 has also been reported to be important for CAF activation in pancreatic and oral squamous cell carcinomas." (PMID 38269089, 2023).
osteoarthritis (3 papers, 2021 to 2024). A noninflammatory degenerative joint disease occurring chiefly in older persons, characterized by degeneration of the articular cartilage, hypertrophy of bone at the margins and changes in the synovial membrane. "In addition to the three miRNAs identified in our study, recent research has expanded our understanding of miRNAs in osteoarthritis (OA), highlighting their significant involvement in key OA-associated signaling pathways, including MMP13, STAT3, SMAD2/3, NOTCH3/Notch, and NF-κB." (PMID 39796139, 2024). "While NOTCH3 activation was shown to promote chondrogenic differentiation, suggesting that NOTCH3 activation in knee joint may protect cartilage and inhibit meniscus degeneration, its effect on osteoarthritis still requires further studies." (PMID 37026620, 2023). "Moreover, recent studies have further revealed the extensive roles of miRNAs in osteoarthritis, particularly in crucial pathways such as MMP13, STAT3, SMAD2/3, NOTCH3/Notch, and NF-κB signaling." (PMID 39796139, 2024).
pituitary adenomas (3 papers, 2008 to 2017). "Upregulation of NOTCH3 gene expression was described in non functioning pituitary adenomas, and in prolactinomas compared to normal pituitaries." (PMID 28915655, 2017). "We provide the first description of the differential expression of Jagged1 in human pituitary adenomas and its correlation with Notch3." (PMID 23426998, 2013). "In the current study, we investigated the role of Notch3 and its ligand Jagged1 in various types of pituitary adenoma as well as in normal pituitary glands." (PMID 23426998, 2013). "Overall, pituitary adenomas (n=15) demonstrated a 4-fold increase in Notch3 mRNA expression compared with normal pituitary tissue; however, this increase was not significantly different (P=0.100)." (PMID 23426998, 2013). "However, the exact mechanism of the interaction between Notch3 and Jagged1 in pituitary adenomas remains to be elucidated." (PMID 23426998, 2013). "In human pituitary adenomas we showed NOTCH1-4 receptors, JAGGED1 ligand and HES1 target gene expression with positive correlations between NOTCH1,2,4 and HES1, and NOTCH3 and JAGGED1 denoting Notch system activation in a subset of tumors." (PMID 28915655, 2017). "As a group, pituitary adenomas (n=17) did not demonstrate an elevated expression of Notch3 protein compared with normal pituitary tissue (n=3, P=0.335)." (PMID 23426998, 2013). "The expression of Notch3 mRNA and protein was significantly elevated in the NFPAs compared with normal pituitary tissue, whereas all pituitary adenomas do not overexpress Notch3." (PMID 23426998, 2013). "Pituitary adenomas may over-express certain growth factors or their receptors such as FGF-2, EGF, TGF-α, EGF-R, Notch-3, FGF-R1, and VEGF." (PMID 18081553, 2008). "However, the role of Jagged1 in pituitary adenomas has not yet been demonstrated, and there is no direct evidence of the function of Notch3 in GH- and PRL-secreting adenomas." (PMID 23426998, 2013).